APOE (apolipoprotein E)
Diseases named in the same sentence as APOE in open-access papers (continued):
Sharing a sentence is not in itself a finding about the gene and the disease.
Alzheimer disease (continued). "There was a significant negative interaction between APOE ε4 status and type 2 diabetes on the risk of dementia for all-cause dementia (HR for interaction term 0.62, P = 0.011), as well as Alzheimer’s disease (HR 0.46, P = 0.047), but not for mixed dementia or vascular dementia." (PMID 37091584, 2023). "Consequently, studying the mRNA expression of APOE could potentially provide a new perspective on the understanding of the pathology of Alzheimer’s disease." (PMID 36092303, 2022). "Interestingly, other than APOE, none of the genes encoding the 28 polygenic score-associated proteins are near (<500kb) loci implicated in Alzheimer’s disease GWAS efforts." (PMID 36048760, 2022). "In the studies that reported stratified results according to ApoE ε4 carrier status, the pooled RR between PA and all-cause dementia or Alzheimer’s disease was similar for ApoE ε4 carriers (RR 0.81, 95% CI 0.67 to 0.98) and non-carriers (RR 0.72, 95% CI 0.56 to 0.92)." (PMID 35301183, 2022). "However, despite a high frequency of Apolipoprotein E allele amongst those of African ancestry, it does not appear to be as important a risk gene for Alzheimer’s disease development in this population." (PMID 35731202, 2022). "The ERN1 association identified from the TRAPD burden test also mimics an exome-wide association study of APOE ε4 non-carrier Alzheimer’s disease which found a rare synonymous variant in ERN1 (rs56201815) as being associated with late-onset Alzheimer’s disease (LOAD)." (PMID 36175824, 2022). "Our aim was to investigate the association of the genetic variant, rs744373 in the bridging integrator 1 gene (BIN1), the strongest genetic risk factor for Alzheimer’s disease after the APOE ε4 allele, with different cognitive domains among non-demented older men." (PMID 36280690, 2022). "Of particular interest to the current work is that CMBs also associate with Alzheimer’s disease and APOE ε4 has been linked directly to CMBs in non-demented elderly patients, as well as neurovascular disease, decreased neuronal repair, and increased brain atrophy." (PMID 35814456, 2022). "The full PRS and PRS.no.APOE contributed 10.1 and 2.4% to Alzheimer’s disease risk, respectively." (PMID 35169705, 2022). "However, they also found that progression from amyloid accumulation and mild cognitive impairment to Alzheimer’s disease was better determined by polygenic risk scores, not APOE status." (PMID 36056235, 2022). "Likewise, a study in Alzheimer's disease showed that the decreased structural stability of apoE may contribute to the formation of neurotoxic fibrils." (PMID 35602473, 2022). "Indeed, it isplausible that individuals who do not carry the risk variant of the APOE genefor hypercholesterolaemia and Alzheimer’s disease were not motivated to changedietary behaviour." (PMID 34156333, 2022). "Apolipoprotein E (ApoE) may play a protective role in neuronal activity and injury repair, whereas its toxic fragments are reported to induce neurodegeneration and neurocognitive impairment in patients with Alzheimer's disease (AD)." (PMID 35810473, 2022). "Alzheimer’s disease (AD) is a frequent and disabling neurodegenerative disorder, in which astrocytes participate in several pathophysiological processes including neuroinflammation, excitotoxicity, oxidative stress and lipid metabolism (along with a critical role in apolipoprotein E function)." (PMID 36362415, 2022). "To elucidate the contribution of rs1360780 FKBP5 C/T alleles to aging and longevity, we genotyped FKBP5 in a cohort of 800 non-demented and Alzheimer’s disease (AD) subjects of different age, taking into account the allele state of ApoE ε4, the major risk factor for AD." (PMID 35205209, 2022). "Interestingly, recent studies of single cell transcriptomics have shown that the APOE gene was repressed in Alzheimer’s disease oligodendrocyte precursor cells (OPC), oligodendrocyte, and astrocyte subclusters, while it was increased in the microglial AD subcluster." (PMID 33731156, 2021).
Alzheimer disease (continued). "However, the lack of association between the ApoE-ε4 allele and SA in this study suggests that not all interventions directed at Alzheimer’s disease would also be beneficial for SA." (PMID 34786016, 2021). "However in a mouse model of Alzheimer’s disease investigating how sex and apolipoprotein E (APOE) genotype influences microglial interactions and disease pathology, females exhibited higher levels of microglia and amyloid burden compared to males expressing either APOE3 or APOE4 genotypes." (PMID 34222870, 2021). "Although the association between sleep duration and Aβ burden was not altered by age, sex, or APOE status, attention to sleep duration may be important for those at higher risk for preclinical Alzheimer disease." (PMID 34297074, 2021). "Apolipoprotein E (APOE), a major cholesterol carrier that is involved in the regulation of lipid transport, neuronal signaling, and amyloid-beta aggregation and clearance has long been established as a major risk factor for late onset Alzheimer’s disease (LOAD)." (PMID 34209762, 2021). "There was a higher proportion of APOE ε4 homozygotes and heterozygotes in the Alzheimer’s disease cohort but with a similar distribution of these alleles between the infection and non-infection Alzheimer’s disease groups." (PMID 33723589, 2021). "Future work should focus on replicating our initial findings and establishing whether a specific dose of supplementary DHA, at a particular time in the preclinical disease course can have a positive impact on Alzheimer’s disease progression in APOE ε4 carriers." (PMID 34007965, 2021). "Another prospective study of 815 US residents aged 65 years or older, free of dementia at baseline, and with a median follow-up of 3.9 years showed that dietary vitamin E intake was inversely associated with risk of Alzheimer disease only among persons who were APOE ε4 noncarriers." (PMID 34385499, 2021). "Furthermore, age and APOE e4 carriage interact with sex: female e4 heterozygotes have an increased risk of Alzheimer’s disease 5 years earlier than non-carriers." (PMID 33615215, 2021). "Here, we show that docosahexaenoic acid’s association with entorhinal volume and spatial navigation ability is modulated by the APOE genotype, with non-significant or inverse associations found in APOE ε4 carriers who are genetically-at-risk of Alzheimer’s disease." (PMID 34007965, 2021). "Patients with an atypical Alzheimer’s disease variant, such as early-onset Alzheimer’s disease or a missing APOE E4 genotype show only mild or no hippocampal atrophy, but, instead, present with considerable posterior cortical atrophy, e.g., the precuneus region in early-onset Alzheimer’s disease." (PMID 33660199, 2021). "Since APOE ε4 allele carriage is considered the greatest non-modifiable risk factor for Alzheimer’s disease, this is an important confounding factor that should be evaluated in future studies, as a potential moderator of the relationship between PA and brain health." (PMID 34916921, 2021). "Apolipoprotein E (APOE), having three common protein isoforms (ɛ2, ɛ3, and ɛ4), is involved in neuronal repair and plasticity and carriers of the ɛ4 allele are at increased risk for neurological conditions such as Alzheimer’s disease (AD) and poor outcome following moderate and severe TBI." (PMID 33499167, 2021). "This study aims to investigate the mechanisms by which apolipoprotein E (APOE) genotype modulates the relationship between low‐density lipoprotein receptor‐related protein 1 (LRP1) rs1799986 variant on the default mode network (DMN) and cognition in Alzheimer's disease (AD) spectrum populations." (PMID 34387022, 2021). "The aim of this study was to investigate whether cognitive performance was equally influenced by Apolipoprotein E (APOE, with its three alleles, e2, e3, and e4) in patients with subjective cognitive decline (SCD), mild cognitive impairment (MCI), and Alzheimer’s disease (AD)." (PMID 34194377, 2021).
Alzheimer disease (continued). "The genomic region chr19:44,902,730–44,915,006, comprising the whole APOE gene as well as its promoter and small parts of TOMM40 and APOC1, was selected as a target region because it includes several SNVs and haplotypes previously linked to Alzheimer’s disease and other age-related diseases." (PMID 33271988, 2020). "Alzheimer’s disease is a neurodegenerative disease with a variety of pathogenesis, including Cholinergic hypothesis, Amyloid beta (Aβ) hypothesis, Tau hypothesis, Excitotoxic hypothesis, Oxidative stress hypothesis, Apolipoprotein E (ApoE) hypothesis." (PMID 32065782, 2020). "It is suggested that APOE genotype may be useful in the diagnosis of Alzheimer's disease." (PMID 33101544, 2020). "However, similar variants in the same gene could also be protective for one disease and confer risk for another disease, such as demosntrated for APOE in AMD and Alzheimer’s disease." (PMID 31934346, 2020). "•Genes outside APOE region could trigger Alzheimer's disease in older ages (age≥80 years)." (PMID 32464432, 2020). "After adjusting for age, sex, years of education and APOE-ε4 carrier status, PHS (status) showed a strong association in all three contrasts involving CN subjects (P ≤ 4.32e-06), while there was only a nominally significant effect between MCI and Alzheimer’s disease (P = 0.044)." (PMID 32226939, 2020). "Given that the two distinct molecular pathologies—tauopathy and β-amyloidosis—that define Alzheimer’s disease are highly correlated, we wanted to establish whether APOE or Alzheimer’s disease PRS had a specific (or primary) effect on a particular aspect of neuropathology." (PMID 33376986, 2020). "In a case-control study using cerebrospinal fluid biomarkers, Hana Saddiki and colleagues investigate how age is related to the association between Apolipoprotein E genotype and Alzheimer's disease, among individuals with and without Alzheimer's disease in Europe and the US." (PMID 32817639, 2020). "No APOE ε4 allele was present in 12 participants with a mean age of reported onset at 52.8 years, a family history in 3/12, no young onset family history and 3 participants with negative autosomal dominant Alzheimer’s disease genetic testing." (PMID 32671341, 2020). "The situation may be analogous to that for Alzheimer’s disease where the APOE ε4 (Apolipoprotein E) risk allele has a frequency of only 14% and does not fully explain the Alzheimer’s disease age-of-onset risk." (PMID 32082115, 2020). "In conclusion, by combining common genetic variation in four genes with possible function in the blood–brain barrier, we found an increased risk of Alzheimer’s disease, all dementia and suggested vascular dementia with increasing weighted/simple allele score groups independent of the APOE ε4 allele." (PMID 30830563, 2019). "However, their associations with late-life cognitive disorders are relatively weak, although a polygenic risk score outside the APOE ε4 locus may help improve risk prediction for MCI and Alzheimer’s disease." (PMID 31214016, 2019). "However, this apparent reversed labelling reinforces the principal findings of this paper that APOE-ɛ4 carrier status in young controls is principally revealed by hyperconnectivity, whilst Alzheimer’s disease leads to hypoconnectivity in a larger, but overlapping, set of connections." (PMID 31038453, 2019). "We felt that the potential value of having this information to participants outweighed the risks, and participants who expressed an interest in receiving their APOE results were counseled extensively that APOE status represents a risk factor for Alzheimer's disease and is not definitive." (PMID 30487145, 2018). "The best evidence linking APOE-ε4 with poor outcomes comes from studies of severe TBI, with patients experiencing worse cognitive and functional impairments, β-amyloid deposition, prolonged coma, as well as a synergistic influence on the risk of developing Alzheimer’s disease." (PMID 30223506, 2018).
Alzheimer disease (continued). "The reason for choosing clusterin, and not any of the other Alzheimer’s disease GWAS index variants is that clusterin is a biologically plausible lipid molecule with dual functions in the brain and in the peripheral circulation just like apolipoprotein E." (PMID 29534716, 2018). "Our work represents a building stone towards a better understanding of the strong anti-atherogenic effect of apoE and the models we are proposing could prove useful in the study of lipidated apoE in totally different contexts, such as understanding its role in Alzheimer’s disease." (PMID 29933361, 2018). "Whether genetic variation in CLU is associated with Alzheimer’s disease, lipid metabolism, or atherosclerosis-related diseases in the general population and whether these associations are independent of the APOE genotype remains unexplored." (PMID 29534716, 2018). "Yet, these measures have rarely been assessed in parallel in the context of mild cognitive impairment (MCI) and furthermore it has not been examined if they are related to risk factors of Alzheimer’s disease (AD) such as amyloid deposition and apolipoprotein ε4 (ApoE) allele occurrence." (PMID 29081745, 2017). "In addition, APOE and APCS were associated with both Parkinson's disease and Alzheimer's disease." (PMID 26909022, 2016). "However, microglia did not change the relationship between APOE genotype and dementia (analysis not shown), reinforcing APOE genotype as the stronger risk factor for Alzheimer’s disease." (PMID 27256292, 2016). "ApoE polymorphic alleles have been identified as the main genetic determinants of AD risk; specifically, apoE-ε4 has been associated with increased toxicity and loss of neuroprotective function in the pathogenesis of Alzheimer's disease, dependent on or independent of Aβ accumulation." (PMID 27034849, 2016). "This age-related allelic difference in methylation level may provide mechanistic support for previous findings linking the A allele of rs405509 to greater risk of myocardial infarction, premature coronary heart disease, and Alzheimer's disease, but lower plasma concentration of ApoE." (PMID 25476875, 2015). "Thus, although APOE ε4 allele is a strong genetic risk factor for Alzheimer’s disease, it does not seem to impact intelligence at young ages." (PMID 26574747, 2015). "Finally, longitudinal analysis also detected another significant SNP rs439401, which also belongs to gene APOE and is very close to SNP rs4420638; SNP rs4420638 was shown to be related to late on-set Alzheimer's disease, dyslipidemia, schizophrenia, myocardial infarction and psychological stress." (PMID 25098835, 2014). "In addition, we found risk variants for late-onset neurodegenerative diseases, such as the APOE ε4 allele that was even present in a homozygous state in one centenarian who did not develop Alzheimer's disease." (PMID 25333069, 2014). "Polymorphisms within the apolipoprotein-E (APOE), Methylenetetrahydrofolate reductase (MTHFR) and Angiotensin I-converting enzyme (ACE) genes has been associated with cardiovascular and cerebrovascular disorders, Alzheimer’s disease and other complex diseases in various populations." (PMID 24679048, 2014). "The APOE ε4 allele (comprising the T allele of rs429358 and the C allele of rs7412 in cis) serves to reduce the age of onset of Alzheimer disease from 78.4 years in patients lacking the allele, to 75.3 in heterozygous carriers to 72.9 in carriers of two APOE ε4 alleles." (PMID 23820649, 2013). "This could explain the lack of finding of a single genetic risk factor (other than ApoE) for late onset Alzheimer’s disease." (PMID 24252508, 2013). "The dysfunction of the signaling pathways downstream of mTOR may represent a risk factor for Alzheimer’s disease and is independent of the ApoE status of the patients." (PMID 24252508, 2013).
Alzheimer disease (continued). "The patients who are classified as in normal condition without dementia will be diagnosed to have Alzheimer's disease in the next year with a probability ranging from 2.6% (Age = 55, no APOE-4 allele) to 21.1% (Age = 85, two APOE-4 alleles), depending on the patient's age and APOE-4 allele number." (PMID 24073268, 2013). "Although nearly 2000 genes have been implicated in the etiology of late onset Alzheimer's disease over the past two decades, it was only in 2009 that two large-scale genome-wide association studies replicated associations between LOAD and genes other than APOE." (PMID 24278680, 2012). "Although GWAS studies have reported significant associations between rs2075650 and Alzheimer's disease, brain imaging, total cholesterol, and CRP plasma levels, no analyses were performed to determine whether these associations are APOE independent." (PMID 21418511, 2011). "Similarly, a recent report on rapidly progressive Alzheimer's disease has found that both APOE and PRNP may modulate the phenotypic expression of the disease." (PMID 21799773, 2011). "Liposomes functionalized with phosphatidic acid and ApoE-derived peptides have successfully penetrated the BBB, leading to reduced amyloid-beta aggregation and enhanced Alzheimer’s disease therapy." (PMID 40286158, 2025). "In addition, the inclusion of genetic factors such as APOE genotype and Alzheimer’s disease–related blood biomarkers would be valuable to explore whether this ET subgroup shares biological vulnerability pathways with prodromal Alzheimer’s disease." (PMID 41209541, 2025). "Pharmacological activation of Liver X Receptor (LXR) has been shown to increase expression of ApoE and ABCA1 proteins, reducing neurodegeneration in murine models of Alzheimer’s disease." (PMID 41225791, 2025). "In this example, the terms are Neuronal ApoE, MHC-I expression, selective neurodegeneration, and Alzheimer’s disease." (PMID 40114255, 2025). "ApoE lipidation, which was controlled by ABCA1 activity, was reported to play a central role in β-amyloid (Aβ) accumulation and Alzheimer’s disease (AD) pathology." (PMID 40526435, 2025). "Apolipoprotein E (APOE) is essential for lipid homeostasis and has been extensively studied in the central nervous system, particularly in the context of Alzheimer’s disease (AD)." (PMID 40667248, 2025). "Using longitudinal data from the Alzheimer’s Disease Neuroimaging Imitative (ADNI) and survival analysis, we show that APOE contributes to progression from A−T− to A+T−, but only marginally from A+T− to A+T+." (PMID 38820112, 2024). "An additional 31 genes in the Alzheimer’s Disease KEGG pathway lose rhythmicity with aged serum; these include amyloid precursor protein (APP) and apolipoprotein E (APOE)." (PMID 37808824, 2024). "To prepare APOE and TREM2 ASO efficacy studies in disease-relevant mouse models of Alzheimer’s disease, we explored if ASOs can also target disease-relevant genes in human microglia in vivo." (PMID 38654375, 2024). "Proteins known to be involved in Alzheimer’s disease progression, (such as CLU, APOE, and ADAM10) and Parkinson’s Disease (such as PARK7 and VPS35) were also identified, suggesting a potential role of GDE2-released EVs in neurodegeneration." (PMID 39272985, 2024). "The results of the analysis demonstrated significant inhibition in the progression of Alzheimer's disease (AD) in NKRF knock‐in (NKRF) and ZBTB17 knockout (ZBTB17−/−) mice compared to the model mice (3×Tg and 3×Tg/ApoE−/− + HFD)." (PMID 38738952, 2024). "In summary, there are numerous target pathways that intersect with both myelin repair and Alzheimer's disease pathophysiology, including APP processing, ApoE signaling, and tau-Fyn processing." (PMID 39285941, 2024). "For example, APOE and SPP1 mRNA participate in lipid metabolism and are related to Alzheimer’s disease." (PMID 38892402, 2024).